MYL9 (myosin light chain 9)
Diseases named in the same sentence as MYL9 in open-access papers (continued):
Sharing a sentence is not in itself a finding about the gene and the disease.
bronchopulmonary dysplasia (1 paper, 2020). Bronchopulmonary dysplasia is a chronic respiratory disease that results from complications related to lung injury during the treatment of infant acute respiratory distress syndrome in low-birth-weight premature infants or from abnormal lung development in older infants. "At present, it is unclear if additional phenotypes are seen in the proband (e.g., white matter loss, kidney stones, bronchopulmonary dysplasia, etc.) can be linked to MYL9, and additional genetic testing has not been performed." (PMID 33031641, 2020).
cervical squamous cell carcinoma (1 paper, 2024). A squamous cell carcinoma arising from the cervical epithelium. "Expression of the MYL9 gene is positively correlated with the expression of CAFs in BRCA, BLCA, cervical squamous cell carcinoma and endocervical adenocarcinoma (CESC), CHOL, COAD, STAD, esophageal carcinoma (ESCA), kidney renal papillary cell carcinoma (KIRP), and LIHC." (PMID 39768172, 2024).
colitis (1 paper, 2020). Inflammation of the colon. "Anti-Myl9/12 Ab treatment of mice with DSS-induced colitis prolonged their survival, and reduced the loss of body weight and DAI in comparison to mice with control Ab treatment." (PMID 33584659, 2020). "It is also possible that CD69-independent mechanisms contribute to the inhibitory effect of anti-Myl9/12 Ab treatment in DSS-induced colitis." (PMID 33584659, 2020). "In the present study, we detected Myl9/12 protein very easily in the inflamed gut, not only in mice with colitis induced by the administration of DSS, but also in UC and CD patients." (PMID 33584659, 2020). "We herein report that the expression of Myl9/12 was highly detected in the inflamed guts of mice with DSS-induced colitis as well as in IBD patients." (PMID 33584659, 2020). "Notably, the plasma levels of IL-6, IL-1β, and TNFα from DSS colitis mice were significantly diminished in mice that received anti-Myl9/12 Ab treatment in comparison to those that received control Ab treatment." (PMID 33584659, 2020). "Notably, our data showed that anti-Myl9/12 Ab treatment ameliorated DSS-induced colitis, and our previous study showed that anti-CD69 Ab treatment ameliorated DSS-induced colitis." (PMID 33584659, 2020). "To determine the involvement of Myl9/12 in the pathogenesis of colitis, we first examined whether the Myl9/12 expression was increased under the inflammatory conditions in the colon." (PMID 33584659, 2020). "Furthermore, anti-Myl9/12 Ab treatment of mice with DSS-induced colitis ameliorated the inflammation, indicating that Myl9/12 regulates the pathogenesis of IBD." (PMID 33584659, 2020). "Furthermore, anti-Myl9/12 Ab treatment ameliorated DSS-induced colitis, suggesting that Myl9/12 Ab may have therapeutic potential in IBD." (PMID 33584659, 2020). "We demonstrated the strong expression of Myl9/12 in the inflamed gut of IBD patients and mice with DSS-induced colitis." (PMID 33584659, 2020). "In the present study, we detected the high expression of Myl9/12 in inflamed tissues from both UC and CD patients, as well as in mice with DSS-induced colitis, and CD69-expressing cells were preferentially located close to Myl9/12-positive vessels at the inflammatory sites." (PMID 33584659, 2020). "To this end, we used a DSS-induced colitis model, which was established by treating wild-type C57BL/6 mice with 2% DSS, which was administered in their drinking water for 7 days, and used an antibody that can detect Myl9, Myl12a, and Myl12b." (PMID 33584659, 2020).
endometrial polyp (1 paper, 2024). A benign nodular lesion protruding above the surface of the endometrium. "Relevant critical genes were downregulated in endometrial polyps, including ACTA2, KCNMB1, KCNMB2, PPP1R12B, MYL9, and ACTG2." (PMID 38473810, 2024).
endothelial dysfunction (1 paper, 2011). In vascular diseases, endothelial dysfunction is a systemic pathological state of the endothelium (the inner lining of blood vessels) and can be broadly defined as an imbalance between vasodilating and vasoconstricting substances produced by (or acting on) the endothelium. "If Myl9 ectopic expression causes endothelial dysfunction, it may explain the increased signs of arterial constriction in the aging vasculature." (PMID 22003410, 2011).
infarction (1 paper, 2024). A localised pathological necrosis of tissue resulting from obstruction of the blood supply usually by a thrombus, an embolus, or vascular torsion. "In contrast, the downregulation of proteins such as ACTN1, MYL9, CSRP1, COMP, and PI16, which are closely associated with muscle cell development and contractility, suggests a disruption in muscular and structural integrity within the heart in the acute phase post-infarction." (PMID 39513871, 2024).
Kawasaki disease (1 paper, 2025). A rare inflammatory disease characterized by an acute febrile, systemic, self-limiting, medium-vessel vasculitis primarily affecting children. "An increase in the plasma Myl9 concentration has also been confirmed in Kawasaki disease." (PMID 39879907, 2025). "Moreover, Myl9, a ligand for CD69, is involved in various chronic inflammatory diseases, such as allergic airway inflammation, inflammatory bowel disease, and Kawasaki disease." (PMID 39879907, 2025).
keloid (1 paper, 2007). An irregularly shaped, elevated mark on the skin caused by deposits of excessive amounts of collagen during wound healing. "Elevated expression of DES, MYH11, MYL9 and SMTN in leiomyomas and several KRTs in keloids and scars reflects the cellular composition of these tissues." (PMID 17718906, 2007).
leukemia (1 paper, 2016). A malignant (clonal) hematologic disorder, involving hematopoietic stem cells and characterized by the presence of primitive or atypical myeloid or lymphoid cells in the bone marrow and the blood. "In megakaryocytic cells, MYL9 expression is regulated by RUNX1, a major hematopoietic transcription factor whose haplo-deficiency is associated with familial thrombocytopenia, platelet dysfunction, and predisposition to leukemia." (PMID 26910538, 2016).
lung disease (1 paper, 2019). "Thus, NSCLC cells respond to TGFβ-stimulation with upregulation of several cancer type unspecific (VIM, MYLK, MYL9, TPM1) but also more lung disease specific (MYH15) proteins." (PMID 31113982, 2019).
lymphoid cancer (1 paper, 2012). "However, transcription of cytoskeletal regulators like MYH9 and MYL9 is elevated in different non-lymphoid cancer cell lines, which depend on MRTFs and SRF for cell spreading, adhesion, and motility." (PMID 22385615, 2012).
malaria (1 paper, 2024). Malaria is a serious and sometimes fatal disease caused by a parasite that commonly infects a certain type of mosquito which feeds on humans. "MYL9 has been reported by one study to be expressed during treatment and recovery from malaria, and could potentially be involved in promoting an adaptive immune response to infection, although this will require further validation and examination." (PMID 39162546, 2024).
malignant glioma (1 paper, 2022). A grade III or grade IV glioma arising from the central nervous system. "Of the 12 overexpressed genes, ABCC3, COL8A1, IBSP and PDPN are reportedly associated with GBM, while CTHRC1, PDLIM4 and MYL9 are associated with high-grade and malignant gliomas, respectively." (PMID 35456975, 2022).
metastatic cancers (1 paper, 2024). A carcinoma which has spread from the original site of growth to another anatomic site. "There is much focus on MYL9 due to its influence on cancer-causing pathways and its ability to be a prime candidate for therapeutics to treat metastatic cancer by targeting its invasive ability." (PMID 39768172, 2024). "It is important to note that MYL9 was correlated with more immune markers in metastatic cancers than in normal tissues; ~60–70/80 were immune marker hits compared with ~20/70 in normal tissues." (PMID 39768172, 2024). "The human atlas genome demonstrates that MYL9 is lowly expressed in several metastatic cancer cell lines, suggesting a role as a metastatic suppressor." (PMID 39768172, 2024).
Obesity (1 paper, 2022). Accumulation of substantial excess body fat. "In mice treated with HFLPD, this expression was reduced; this suggested that our supplemented probiotic might be efficient in protecting the liver from diet-induced obesity and metabolic changes in the liver by inhibiting the carcinogenic marker MYL9." (PMID 35743193, 2022).
osteosarcoma (1 paper, 2022). A usually aggressive malignant bone-forming mesenchymal neoplasm, predominantly affecting adolescents and young adults. "Furthermore, miR-663a promotes proliferation and migration of osteosarcoma by targeting MYL9." (PMID 34974798, 2022).
pancreatic cancer (1 paper, 2022). "We demonstrated that MYL9 inhibition caused cell cycle arrest in the G0/S phase in pancreatic cancer cells." (PMID 34821071, 2022). "Using the data sets extracted from the GENT2 database, we showed that the expression level of MYL9 was upregulated in pancreatic cancer tissues, compared with that in normal tissues." (PMID 34821071, 2022). "Second, we demonstrated that the inhibition of MYL9 suppressed the invasive ability of pancreatic cancer cells." (PMID 34821071, 2022). "We demonstrated that the pattern of MYL9 expression in pancreatic cancer tissues was related to poor prognosis in patients in the overall survival and distant metastasis free survival." (PMID 34821071, 2022). "The results of our study suggest that MYL9 expression is a crucial prognostic biomarker and a potential therapeutic target for pancreatic cancer." (PMID 34821071, 2022). "Furthermore, the inhibition or overexpression of MYL9 may change the level of MYL9 phosphorylation in pancreatic cancer patients." (PMID 34821071, 2022).
ulcer (1 paper, 2019). "Increased Myl9 and Lgals7 levels might demonstrate a tendency in the ulcer areas to progress to cancerous lesions." (PMID 31391093, 2019).
tumor (50 papers, 2013 to 2025). "For example, genetic manipulation of DEFA3, MMP11, or MYL9 in APC Min/+ mice would directly reveal their causal roles in tumor initiation, progression, or metastasis." (PMID 41009818, 2025). "We found that high expression of MMP11 and MYL9 genes was negatively correlated with tumor mutation burden (TMB) scores (p < 0.05)." (PMID 41009818, 2025). "In the PPI results, we observed that molecules such as MAPK14, ATP6V1, Itgbs, MB2, STAT3, PKM, ACSS3, and MYL9, which are associated with signal transduction, inflammation, and tumor invasion, exhibited more active interactions with other molecules." (PMID 38203782, 2024). "Subsequently, we analyzed the relationship between MYL9 and tumor mutation burden (TMB) and microsatellite instability (MSI) in these tumors." (PMID 37926835, 2023). "Immune cell infiltration is associated with tumor prognosis, and although some biological information analysis indicated that MYL9 has an effect on CRC tumor immune cell infiltration, there is a lack of data verification." (PMID 37926835, 2023). "Multivariate analysis revealed that high MYL9 expression in tumor cells was an independent and significant risk factor affecting OS after curative treatment (hazard ratio = 2.254, 95% confidence interval = 1.347–3.771, p = 0.002)." (PMID 28388691, 2017). "It was notable that downstream of PPP1CC and ROCK1 was MYL9, which was a famous hallmark tumor gene." (PMID 27634882, 2016). "We analyzed the relationship between MMP11 and MYL9 gene expression and tumor mutational burden." (PMID 41009818, 2025). "Furthermore, multivariate analyses revealed that elevated MYL9 expression in tumor cells was an independent and significant risk factor affecting recurrence and survival after curative resection." (PMID 28388691, 2017). "Pseudo-time trajectory analysis revealed increased expression of MMP11 and MYL9 in later stages of tumor progression." (PMID 41009818, 2025). "For instance, high MYL9 expression in tumor cells had poorer overall survival (OS) and recurrence-free survival in ESCC, demonstrating that MYL9 is an independent factor affecting OS after curative treatment therapy." (PMID 39768172, 2024). "High expression of MYL9 is known to be a tumor and metastasis promoter for several cancer subtypes, as found by quantifying metastatic nodules on livers and lymphatic metastases in CRC and non-small-cell lung cancer." (PMID 39768172, 2024). "The relationship between MYL9 expression and CRC clinical staging and immunotherapy is closer in CAFs than in tumor cells, and the potential mechanism of MYL9 action in CAFs differs from that in tumor cells." (PMID 37926835, 2023). "Subsequently, we conducted tissue immunofluorescence verification, and the immunofluorescence results indicated that the protein expression level of MYL9 was higher in tumors than in normal tissues and was mainly concentrated in the tumor stroma." (PMID 37926835, 2023). "Although it has been reported that MYL9 expression in tumor tissues is closely related to tumor prognosis, the expression and prognosis of MYL9 in CRC remain controversial and require further confirmation." (PMID 37926835, 2023). "In terms of protein level, western blotting and IHC results of 10 pairs of fresh CRC samples indicated that the total MYL9 protein level in tumor tissues was higher than that in normal tissues." (PMID 37926835, 2023). "Through immunohistochemical analysis, we confirmed that MYL9 was expressed in the tumor‐cell cytoplasm and membrane." (PMID 34821071, 2022). "This suggested that the expression level of MYL9 was closely related to the penetration of tumor DC." (PMID 34729929, 2022). "Recently, many studies showed that MYL9 played the role of a promoter in tumor invasion and metastasis." (PMID 34729929, 2022).
tumor (continued). "Although a large amount of evidence regarding the role of MYL9 in the promotion of tumor invasion and metastasis has been uncovered, the clinical significance of MYL9 in human tissues differs depending on the tumor type." (PMID 34821071, 2022). "In summary, five candidate genes (TIMP1, SPARCL1, MYL9, TPM2, and CNN1) were finally characterized as the hub gene associated with tumor recurrence in CRC." (PMID 33897765, 2021). "In the 136 ESCC samples, high MYL9 expression in the tumor cells significantly correlated with histological differentiation (p = 0.028), recurrence (p = 0.01), and vital status (p < 0.01)." (PMID 28388691, 2017). "Despite much evidence supporting the promoter role of MYL9 in tumor invasion and metastasis, it has been demonstrated that its clinical significance in human tissues differs by tumor type." (PMID 28388691, 2017). "MYL9 expression levels were most closely related to tumor differentiation among the conventional clinicopathological characteristics of ESCC." (PMID 28388691, 2017). "We analyzed the relationship between MYL9 expression levels in tumor cells and the clinicopathological characteristics." (PMID 28388691, 2017). "Patients with high MYL9 expression in the tumor cells had poorer overall survival (OS) and recurrence-free survival." (PMID 28388691, 2017). "Additional research regarding MYL9 expression and status for tumor cell differentiation in ESCC is required." (PMID 28388691, 2017). "Based on MYL9 expression levels in the tumor cell cytoplasm, the patients were divided into two groups: high MYL9 expression (high expression in tumor cells) and low MYL9 expression (low expression in tumor cells)." (PMID 28388691, 2017). "MYL9 immunostaining was observed mainly in the cytoplasm of stromal cells and some tumor cells, which was consistent with the expression pattern in ESCC tissues." (PMID 28388691, 2017). "Specifically MYH9 and MYL9 were among the few shared MKL-dependent genes in those two tumor types and our compound reduces expression of both (ca. 2–3-fold) in PC-3 cells." (PMID 27600078, 2016). "These genes included tumor markers (MUC16), genes that control tumor migration (MYL9), metastasis (CEACAM6, VEGFC, CX3CL1, CST1, CCL5, S100A9, IGF1, NOTCH3), cell adhesion (FN1, CEACAM1), and inflammation (TRAF2, NF-κB2 and RelB)." (PMID 26090868, 2015). "This suggests that MMP11 and MYL9 may drive CRC progression by contributing to therapy resistance—possibly through reduced tumor immunogenicity or the establishment of an immunosuppressive microenvironment." (PMID 41009818, 2025). "This binding enhances the expression of MYL9, thereby influencing tumor biology and EMT dynamics." (PMID 39768172, 2024). "Therefore, MYL9 is predominantly expressed in CAFs and can indirectly influence tumor biology and EMT by affecting CAFs protein expression in CRC." (PMID 37926835, 2023). "Immunofluorescence results indicated that ZEB1 and MYL9 were significantly co-located at the interface between tumor cells and CAFs, which may also indicate an interaction between MYL9 and ZEB1 in the tumor EMT or invasion process." (PMID 37926835, 2023). "The results showed that the expression of CRC and MYL9 had a moderately strong correlation with the tumor immune and stromal scores, suggesting that MYL9 may play an important role in the TME." (PMID 37926835, 2023). "Our results showed that MYL9 expression could alter cell migratory ability, which might affect the tumor metastatic potential." (PMID 36589754, 2022). "In this study, we explored the correlation between MYL9 gene expression and CAFs in all types of cancer in the TCGA dataset, finding that there is a significant positive correlation between the two in all kinds of tumor except SARC." (PMID 34729929, 2022). "In addition, we used the GEPIA2 tool to combine all tumor expression data of TCGA and obtained the top 100 genes that correlated with MYL9 expression." (PMID 34729929, 2022).